CHEK1 (checkpoint kinase 1)
Diseases named in the same sentence as CHEK1 in open-access papers (continued):
Sharing a sentence is not in itself a finding about the gene and the disease.
cancer (continued). "Prior in vitro testing of CHEK1 inhibitors has found that only 10-15% of cancer cell lines are sensitive to isolated CHEK1 inhibition." (PMID 26437225, 2015). "There are already a precedent for the roles of unregulated CDC20, RAD51, and CHEK1 in cancer development and progression." (PMID 25763370, 2015). "Fascinatingly, overexpression of miR-424 repressed the expression of checkpoint kinase 1 (Chk1) and substantially inhibited cancer progression." (PMID 23773282, 2013). "Those predictions from our model can better explain why CHEK1 is regarded as a potential chemotherapeutics target for cancer treatments." (PMID 24023735, 2013). "This underscores CHEK1’s crucial role in cell cycle regulation for these cancers." (PMID 41564103, 2026). "The analysis revealed that high CHEK1 expression was significantly associated with cancer grade but not with age, gender, race, pTNM stage, new tumor event type, or smoking." (PMID 41564103, 2026). "Nevertheless, two partial findings could be compared: 1) the prognostic significance of CHEK1 in cancer and 2) the reliability and performance of pathomics models." (PMID 40344565, 2025). "Also, other additional members of the miR‐15 family were confirmed to regulate CHEK1 in BC (hsa‐miR‐15a, hsa‐miR‐15b, and hsa‐miR‐16) or other carcinomas (hsa‐miR‐424)." (PMID 40548926, 2025). "Moreover, previous studies have implicated ACKR3, CHAF1B, CHEK1, and COL11A1 as being involved in cancer cell proliferation, while CA9, CHAF1B, and COL11A1 play roles in cancer invasion and migration." (PMID 38652547, 2024). "Thus far, the research on CHEK1 has mainly focused on cancer, and CHEK1 inhibitors have unique potential in tumor-targeted therapy." (PMID 39199149, 2024). "CHEK1 is a DNA damage sensor that regulates cell cycle progression, DNA damage response and DNA replication, plays an important role in tumorigenesis, especially in cancer prognosis and tumour phenotype." (PMID 38842135, 2024). "Other predicted dysregulated upstream STKs, checkpoint kinase 1 (CHK1) and cyclin-dependent kinase 5 (CDK5), play roles in cell cycle regulation, and their functional aberrations have been linked to diseases such as cancers (Kastan & Bartek 2004, Sharma & Sicinski 2020)." (PMID 36409629, 2023). "This is also the first report demonstrating the association of MRE11 rs2155209, XRCC5 rs828907, LIG4 rs1805388, ATM rs1801516 and RAD51 rs12593359 with survival in HNSCC, as well as the first to indicate that CHEK1 rs558351 may play a role in cancer disease." (PMID 37894339, 2023). "Furthermore, CHEK1 inhibition has the therapeutic potential in the cancer cell lines and mouse model." (PMID 35428780, 2022). "The function of CHEK1 is well known in cancer cells with defective DNA synthesis machinery." (PMID 33884520, 2022). "This might prime cancer cells towards a highly activated CHEK1-mediated cell cycle checkpoint control (which remains active in in vitro culture)." (PMID 35994503, 2022). "CHEK1 was found in previous studies to act as a major regulator of cell cycle progression and its upregulation can lead to the development of several human cancers, including colorectal, lung, stomach, cervical, and gastric." (PMID 36313570, 2022). "It was reported that CHEK1 overexpression leads to the development of human malignant tumors." (PMID 35309118, 2022).
cancer (continued). "In this context, our discovery of the LR/CHEK1 axis as a novel mechanism of miltefosine underlies its preferential cytotoxicity on cancer cells and will help convince the rationale for the further development of APL drugs for cancer treatment." (PMID 34841679, 2021). "In addition, RSKs are found to phosphorylate cell cycle checkpoint components such as checkpoint kinase 1 (Chk1) and Mer11 to suppress DNA damage signaling and possibly increase cancer cell chemoresistance." (PMID 34202904, 2021). "Importantly, the fact that these pharmacological inhibitors for Atr and Chek1, which are already in clinical trials for cancer therapy, showed efficacy in promoting axon regeneration raises the possibility of repurposing these drugs for regeneration therapy." (PMID 34158506, 2021). "Other critical components of the DDR, including ataxia telangiectasia and Rad3-related (ATR), ataxia telangiectasia mutated (ATM), DNA-dependent protein kinase (DNA-PK), Checkpoint kinase 1 (CHK1), Checkpoint kinase 2 (CHK2) and Wee1 kinase (WEE1), are also promising as targets for fighting cancer." (PMID 34885119, 2021). "CHEK1 inhibition is known to increase replication stress in cancer cells." (PMID 34841679, 2021). "Interestingly, the inhibitory effects of miltefosine on cancer cell viability, sphere formation and stem‐related TF expression were significantly blocked by CHEK1 overexpression." (PMID 34841679, 2021). "The expression of CHEK1 was further validated, and demonstrated that the CHEK1 gene may possess either oncogenic or anti-oncogenic characteristics, depending on the type of cancer." (PMID 32178478, 2020). "CHEK1 was found to be overexpressed in some cancer tissues when compared to normal tissues." (PMID 32178478, 2020). "The Oncomine database was used to investigate the transcript expression of CHEK1 in cancers." (PMID 32178478, 2020). "Due to the possibility of CHEK1’s involvement in solid tumors, it may potentially be a target for therapeutic intervention in cancer." (PMID 32178478, 2020). "This study extensively investigated the role of CHEK1 in solid tumors as well as the mechanism by which it can be regulated through molecular docking with human argonaute protein assisted by a known microRNA found to be crucial in cancer (miR-195-5p)." (PMID 32178478, 2020). "This study suggests that CHEK1 could be further studied as a promising biomarker for cancer management." (PMID 32178478, 2020). "Further studies into the interaction between CHEK1 and other co-expressed genes may give further insight into other modes of regulation of this gene in cancer patients." (PMID 32178478, 2020). "Cancers survive this oncogene-induced replication stress (OIRS) by upregulating multiple stress pathways including ataxia-telangiectasia-mutated-and-Rad3-related kinase - checkpoint kinase 1 (ATR-CHK1) signaling." (PMID 32076484, 2020). "The transcription levels of CHEK1 were investigated to explore its role in cancer." (PMID 32178478, 2020). "Overall, CHEK1 genetic alterations in various cancer types are rare." (PMID 33224881, 2020). "Furthermore, CHEK1 is related to different prognosis in distinct types of cancer, and even in particular subgroups of the same tumors." (PMID 31497245, 2019). "CHEK1 has been considered a potential target for cancer therapy." (PMID 25840419, 2015). "IKKε activity may block apoptosis and perpetuate the cell cycle in CHEK1-inhibited cells, thus allowing cancer cells to survive and proliferate with compromised DNA." (PMID 25474241, 2014). "Our findings highlighted the possibility of using CHEK1 modulators as a novel cancer therapy." (PMID 24023735, 2013).
cancer (continued). "CHEK1 tumor associated alternative TSSs usage, which yields transcripts differing only in their 5' untranslated region (UTR), was most widely associated with cancer." (PMID 21999571, 2011). "Furthermore, the inability to activate Chek1 in response to genotoxic stress and to induce cell cycle arrest to allow for DNA repair leads to aberrant mitosis, genomic instability, and cell death, features observed in AEP-deficient cancer cells." (PMID 40012043, 2025). "Interestingly, tetraploid cancer cells showed sensitivity to some mitotic inhibitors, essentially inhibitors of Checkpoint kinase 1 (CHK1), Aurora B, Kinesin-5 (Eg5), Polo Like Kinase 1 (Plk1) and Monopolar spindle 1 (Mps1 also named threonine tyrosine kinase TTK)." (PMID 39940976, 2025). "Therefore, the development of approaches directed to the inhibition of ATR and CHEK1 in malignant neoplasms, particularly in ECE, could increase the effectiveness of therapeutic measures to prevent recurrence/metastases from occurring." (PMID 38669256, 2024). "Therefore, inhibitors blocking CHEK2 and CHEK1 could have dual benefits for female patients: improved cancer cell elimination and oocyte protection." (PMID 37862420, 2023). "By breeding the kinase-dead Chk1 mouse with a conditional allele, we are able to demonstrate that expression of only one kinase-dead allele, but no wild-type allele, of Chek1 is lethal for Myc-induced cancer cells." (PMID 32571801, 2020). "Previous studies reported that inhibiting DNA damage response proteins (poly-ADP-ribose polymerase (PARP) and checkpoint kinase 1 (CHK1)) could activate cGAS-STING-mediated anti-cancer immunity, and enhance the blockade of PD-1 checkpoint and infiltration of cytotoxic T cell." (PMID 33268765, 2020). "Furthermore, inhibitors of TOP2A, TTK, and CHEK1, which are already used for treating certain cancers, could potentially be used in ACC treatment." (PMID 30886771, 2019). "Therefore, we hypothesized that combining TPT with CHEK1 inhibitor may be an effective and feasible approach to maximize the therapeutic index between cancer cells and normal, allowing lower doses of both agents in order to minimize the dose-limiting toxicity." (PMID 25884494, 2015). "Therefore, CHEK1 inhibitors have been developed as anti-cancer agents." (PMID 25474241, 2014). "Two further studies reported broad activity of GEM in combination with CHEK1 inhibition in NSCLC cells, or CHEK1i and WEE1i across several cancer entities other than PDAC." (PMID 39838187, 2025). "The opposite prognostic roles of miR‐195‐5p expression compared to CHEK1 and CDC25A gene expression in luminal BC patients suggested the functional relevance of this miRNA for CHEK1 and CDC25A in this cancer subtype." (PMID 40548926, 2025). "Most of these genes were cell cycle-related genes, including CHEK1, CDK1, RUVBL2, PSMD14, SUPT5H, RBX1, and AURKA, across 28 cancer types." (PMID 38972884, 2024). "Since CDK1, CHEK1, KIF11, PLK1 and TTK was significantly elevated with cancer progression in LUAD and exhibited excellent binding performance with 6-MDS, they were chosen for further validation." (PMID 38783288, 2024). "The findings demonstrated that the hub genes ORC1, CDC6, CHEK1, and MAD2L1 promoted the cell cycle checkpoint signaling, which is essential in cancer progression." (PMID 37945594, 2023). "The inhibition of cell cycle checkpoint proteins, such as ataxia telangiectasia mutated and Rad3-related kinase (ATR) and its major downstream effector checkpoint kinase 1 (CHK1), is another strategy to increase the anti-cancer efficacy of TOP1-ADC." (PMID 36015333, 2022).
cancer (continued). "In our study, high expression of CHEK1 in CCA was dramatically correlated with tumor biological characteristics, such as tumor size, lymph node metastasis, cancer cell proliferation, invasion and migration, and EMT." (PMID 35428780, 2022). "Similar to many metabolic enzymes, PGAM1 asserts a nonenzymatic function, as the physical interaction with checkpoint kinase 1 (Chk1) increases proliferation, specifically in RAS-driven cancer cells." (PMID 36139550, 2022). "In contrast, the siRNA sequences targeting exon 13.3 of CHEK1 exhibited limited influence on the migration and invasion of PDAC cancer cells." (PMID 36713450, 2022). "CHEK1 and WEE1 activation is required to initiate cell cycle arrest to give cancer cells enough time to recover from damage accrued from therapeutic agents." (PMID 35301276, 2022). "CHEK1 and WEE1 are cell cycle proteins whose expression is commonly dysregulated in multiple cancer types." (PMID 35301276, 2022). "For all 56 hub gene candidates, only CHEK1 and UBE2C were found to be significantly correlated with BRCA patient survival and differentially expressed between cancer and normal specimens." (PMID 35903365, 2022). "The Atr-Chek1 network is a key mediator of DDR, and inhibiting DDR has become an attractive concept in cancer therapy." (PMID 34158506, 2021). "RAS is the most commonly mutated gene in MM, and simultaneous inhibition of Checkpoint Kinase 1 (CHEK1) and MK2 MAPK Activated Protein Kinase 2 (MK2) has synergistic effects in suppressing KRAS-mutant cancer." (PMID 34090465, 2021). "In the present study, VEGFA, RRM2, H2AFX, CHEK1, CEP55, CDCA8 and AURKA were significantly upregulated; however, VCL, TPM2 and TPM1 were significantly downregulated in cancer samples of BC." (PMID 34112125, 2021). "There exist a positive correlation between EZH2 and the five genes (CHEK1, MAD2L1, RFWD3, TRAIP, and TTK) in the majority of detailed cancer types as shown in the form of heatmap data." (PMID 34381492, 2021). "Kinome data from the Cancer Dependency Map (DepMap) CRISPR and shRNA screens also support PDAC growth dependency on CHEK1 and ATR expression." (PMID 34852220, 2021). "To summarize, these results suggest that the Atr-Chek1 pathway also functions intrinsically in neurons to inhibit axon regeneration in mammals, a process that may be evolutionarily conserved, and that the anti-cancer drugs targeting Atr-Chek1 may be repurposed for treating neural injury." (PMID 34158506, 2021). "CHEK1, as downstream effector of ATR serine kinase, responds to DNA damage and mediates resistance to chemotherapy across cancer types." (PMID 34760688, 2021). "Although the splicing events of these genes were not reported previously, their gene expression level was linked to tumorigenesis or prognosis of CRC (SERPINA1) or other cancer types (ARHGEF9, CHEK1, HKDC1)." (PMID 32503434, 2020). "CHEK1 is an essential part of the G2/M checkpoint signaling pathway and it is overexpressed in almost all HGSOC, suggesting a need of cancer cells for G2/M checkpoint and arrest to essential DNA repair." (PMID 32605254, 2020). "It is reported that simultaneous inhibition of CHEK1 and AURKA leads to cell cycle arrest and apoptosis of cancer cells." (PMID 32548103, 2020). "For example, phosphorylation of H3.3 on serine 31 expands from pericentromeric regions to whole chromosomes in a checkpoint kinase 1 (CHK1)-dependent manner and contributes to the maintenance of genome integrity in ALT cancer cells." (PMID 33167489, 2020). "In contrast, targeting WEE1 or CHEK1 sensitizes cancer cells to DNA-damaging drugs, supporting WEE1 and CHEK1 as potential targets and chemosensitizers for cancer therapy." (PMID 31387297, 2019). "We found that TOP2A, TTK, CHEK1, and CENPA play critical roles in biological processes that are highly correlated with cancer, such as DNA topological structure, cell cycle progression, and mitosis, thereby suggesting their possible role in cancer development." (PMID 30886771, 2019).
cancer (continued). "Several other proteins such as AURKA, AURKB, CHEK1, BIRC5, CDC25B decreases their local PageRanks in cancer which means they become more controlled." (PMID 29370181, 2018). "Upon DNA damage, HMGA2 increases cancer cell survival through prolonged phosphorylation of ATR and its downstream target checkpoint kinase 1 (CHK1)." (PMID 26799419, 2016). "Three genes - CHEK1, EPHB3, and PIP5K1A - were increased at least 2 fold in expression in more than 50% of the tumor set compared to non-cancer controls." (PMID 25474241, 2014). "The changes observed for CHEK1, OSBPL1A and TCF12 were confirmed in several other cancer types indicating that the change in TSS usage is a general mechanism in cancer biology." (PMID 21999571, 2011). "These include a number of known or potential tumour suppressor genes (BCSC-1, CHEK1, ST14, ATM, P53AIP1), genes with proposed roles in cancer progression (BARX2), apoptosis (PIG8, P53AIP1) and oncogenesis (FLI1, ETS1), and a DNA damage-inducible gene (DDI1)." (PMID 18506147, 2008). "Moreover, based on the blue module genes screened by WGCNA and existing researches, AURKA, TPX2, CHEK1, and PLK1 were found to be highly related to NCAPH and were involved in the regulation of PI3K/AKT pathway in cancer." (PMID 38587786, 2025). "Besides, the expression level of CDK1, CCNA2, CHEK1, KIF11, PLK1 and TTK was significantly elevated with cancer progression in LUAD." (PMID 38783288, 2024). "In addition, the expression level of CDK1, CHEK1, KIF11, PLK1 and TTK was significantly elevated with cancer progression in LUAD." (PMID 38783288, 2024). "DNA topoisomerase II alpha activates cell cycle progression from the G2 to the M phase by inhibiting CHK1 phosphorylation (CHK1, checkpoint kinase 1, is the protein product of the CHEK1 gene), promoting the epithelial-to-mesenchymal transition and cancer cell invasion." (PMID 38136356, 2023). "CHEK1, a member of the CHEK family, is a serine/threonine-specific protein kinase; it is mainly involved in the coordination of DNA repair and is, therefore, an area of great interest in cancer development and therapy." (PMID 35993051, 2022). "Interestingly, four of the six targetable genes, CDK4, RAD50, CHEK1, and MDM2, were involved in two or more major cancer-related pathways." (PMID 33557149, 2021). "In spite of lacking of evidence that has-mir-122-5p directly binds to CHEK1, the inhibitory effect of hsa-mir-122-5p in multiple human cancers has been widely reported." (PMID 32257949, 2020). "The protein levels of CHEK1 and MCM10 were more significant in carcinomas than normal tissues and the differential expressions of KIF23 and TTK could be observed between primary lesions and liver metastases." (PMID 33134313, 2020). "FGF2 and CHEK4 are up-regulated while the expression of CHEK1, WT1, MDM2, BARD1, BMP2, BAMBI, and SOD2, have been reported to be down-regulated in several cancer subtypes, including CRC." (PMID 31623294, 2019).